IL1A (interleukin 1 alpha)
Diseases named in the same sentence as IL1A in open-access papers (continued):
Sharing a sentence is not in itself a finding about the gene and the disease.
periodontitis (continued). "The likelihood of periodontitis in patients with IL-1A and/or IL-1B polymorphism was lower when IL-1RN polymorphism was also present in comparison to IL-1A and/or IL-1B polymorphisms alone." (PMID 29023524, 2017). "IL-1A and IL-1B gene polymorphisms have been considered a risk factor for periodontitis progression in populations of European descent due to a resulting overproduction of pro-inflammatory IL-1α and IL-1β, respectively." (PMID 29023524, 2017). "In our study population, logistic regression analysis showed that polymorphism in IL-1A and/or IL-1B gene was strongly associated with generalized periodontitis (GCP or GAgP)." (PMID 29023524, 2017). "Genetic variations in IL-1A gene were associated with elevated risk to chronic periodontitis by elevated level of this cytokine in gingival fluid, but results are contradictory." (PMID 27918732, 2017). "Three meta-analysis evaluating a polymorphism (-889 C/T) in IL-1A and chronic periodontitis are available in literature and addressed association of this polymorphism and risk of development of chronic periodontitis." (PMID 27918732, 2017). "In both types of periodontitis, IL-1RN polymorphism was significantly associated with a reduced load of P. intermedia, P. gingivalis, and T. forsythia, while IL-1A polymorphism was significantly associated with an increased P. intermedia load." (PMID 29023524, 2017). "Polymorphism in the IL-1A and/or IL-1B gene was associated with a greater likelihood of the presence of periodontitis when the two types (GCP + GAgP) were considered together." (PMID 29023524, 2017). "A combined genotype with single nucleotide exchanges in the IL-1A and IL-1B gene was found to be associated with an increased risk of periodontitis." (PMID 26595831, 2016). "Lots of studies have investigated the importance of genetic polymorphisms (e.g., MCP-1, S100A8, IL-1α, IL-1β, and N-formyl peptide receptor) in aggressive periodontitis." (PMID 28018430, 2016). "This is supported by a recent study in 385 individuals, which concluded that a single nucleotide polymorphism (SNP) in IL-1α was associated with periodontitis." (PMID 25077073, 2014). "Genes known to be associated with peri-implantitis and periodontitis were tested for their presence in our case group; IL-1A, IL-1B, and TNF all appeared in our dataset." (PMID 24921256, 2014). "The purpose of this study was, therefore, to assess the association between the IL-1A C[−889]T and IL-1B C[3954]T polymorphisms and sever chronic periodontitis among Yemenis based on haplotype analysis." (PMID 22778957, 2012). "In the current study, the IL-1A C[−889]T and IL-1B C[3954]T polymorphisms showed strong association with sever periodontitis in the TT versus CT + CC genotype contrast (recessive model)." (PMID 22778957, 2012). "The odds ratio for carriage of IL-1α allele (T/T + C/T genotypes combined to compare with the C/C genotype) was 4.368 (95% CI = 2.309 - 8.264, X2: p < 0.0001) in periodontitis patients." (PMID 23046796, 2012). "Nevertheless, despite the heterogeneity of the findings, the identification of specific IL-1α polymorphisms associated with periodontitis in the Indian population could have potential clinical implications." (PMID 39810806, 2024). "The correlation of periodontitis with IL-1α polymorphism in Indians lacks evidence." (PMID 39810806, 2024). "Varying associations observed between IL-1α polymorphisms and periodontitis subtypes could reflect these underlying differences in disease mechanisms." (PMID 39810806, 2024). "Therefore, this study aims to analyse data from the literature related to the genetic correlation between IL-1α polymorphisms and periodontitis among Indians." (PMID 39810806, 2024).
periodontitis (continued). "Genetic aspects, in particular, the increase in the allelic frequency of single-nucleotide polymorphisms (SNPs) for IL-1 beta (IL-1b) (+3954), SNP IL alpha −889 (IL-1a), and a positive genotype of IL gene increased risk of developing periodontitis within the European Caucasian." (PMID 37998274, 2023). "In another study, the extent of CAL loss was significantly associated with the composite genotype of IL-1A/-1B in smokers, which ensured the information that the polymorphism of IL-1 shows an interaction with smoking, the main modifiable risk factor of periodontitis." (PMID 36429405, 2022). "Additionally, transgenic mice overexpressing IL-1α spontaneously develop periodontal disease, and periodontitis mouse models deficient for IL-1Ra show severe periodontal disease progression." (PMID 35628185, 2022). "Within genotyping to reveal an increased risk of immune reactivity associated with rapid progression of periodontitis, patients H1, H2, H3, H8, H9 and H10 were found to have a positive genotype within the polymorphism in the genes IL1-A (rs1800587), IL1-B (rs1143634) and IL-1RN (rs419598)." (PMID 36290432, 2022). "A current systematic review and meta-analysis showed that although IL-1B is a noteworthy cytokine biomarker in periodontitis development and progression, different IL-1A polymorphisms may have inverse actions in the pathogenesis of periodontitis." (PMID 36429405, 2022). "In addition, the relationship between gene polymorphisms of IL-1α and IL-1β and periodontal disease were significantly different according to the severity of periodontitis." (PMID 34199256, 2021). "For the polymorphisms of the members of Th17 cytokine family, different IL-1α polymorphisms may have inverse actions in the pathogenesis of periodontitis." (PMID 35046930, 2021). "IL-1α − 889 and IL-1β + 3954 were strongly associated with the periodontitis." (PMID 30755190, 2019). "Moreover in other study the smoking was proved as cause of increased risk of attachment loss independently of IL-1A genotype and the interaction between genotype and smoking status caused elevated risk of periodontitis." (PMID 27918732, 2017). "In mixed population, the meta-analysis did not demonstrate significant association between -889 C/T polymorphism in IL-1A gene and risk of chronic periodontitis in T versus C evaluation (OR = 0.97, 95% CI: 0.70, 1.35, P = 0.87) corroborating data previously found in Brazilian population." (PMID 27918732, 2017). "IL1α and IL-1β production upregulates prostaglandin E2 and matrix metalloproteinase and, together with these components, promote the loss of connective tissue and bone in periodontitis lesions." (PMID 23691333, 2013). "IL-1α and IL-1β upregulate prostaglandin E2 and matrix metalloproteinase and, together with these components, promote the loss of connective tissue and bone in periodontitis lesions." (PMID 23691333, 2013). "Moreover, several studies reported an association between IL-1 polymorphisms and periodontitis as well as CHD; one pattern of IL-1 genetic polymorphisms, characterized by the IL-1α+4845 and IL-1β+3954 markers, is associated with periodontitis." (PMID 23691333, 2013). "The detection frequency of the homozygous C allele of IL-1α was similar in the subjects with chronic periodontitis (62%) and control group (55%) (X2, p = 0.18), but in the C/C genotype, the periodontitis patients presented a frequency of 52%, compared to 20% in the control group." (PMID 23046796, 2012). "Additionally, several studies have reported that chronic inflammatory diseases including rheumatoid arthritis, Alzheimer disease, and periodontitis were associated with the T allele of the IL-1α –889C/T polymorphism." (PMID 22216303, 2011).
periodontitis (continued). "An increased risk of developing periodontitis is associated with genetic polymorphisms of IL1A, IL1B, IL6, and TNFA genes and MMP-9 (−1562C/T), ANRIL rs1333048, rs1333042, rs2891168, and rs496892 polymorphisms might have impact on susceptibility to periodontitis, especially in Caucasian individuals." (PMID 41300760, 2025). "Our pilot study showed that the expression of lincRNA‐EPS was restricted in the inflamed mouse periodontal tissues, and its deficiency caused more severe periodontitis, including increased expression of IL‐1α/β, suggesting that it might be related to the inflammasomes in periodontal inflammation." (PMID 37710420, 2024). "Understanding the function of IL-1α in the pathogenesis of periodontitis among the diverse Indian population is critical, since polymorphism can increase the prevalence of disease under disease-promoting environmental conditions, thereby governing the expression of IL1α." (PMID 39810806, 2024). "Different IL-1α polymorphisms may have inverse actions in the pathogenesis of periodontitis." (PMID 35454140, 2022). "Several candidate gene studies have investigated IL-1 polymorphisms (notably IL1A −889 and IL1B +3954/rs1143634) in relation to periodontitis." (PMID 41300760, 2025). "Conversely, testosterone therapy in transgender males increases pro-inflammatory cytokines (e.g., TNF-α, IL-1α, CXCL1) and Th17 cells, potentially heightening inflammation in periodontal tissues and elevating periodontitis risk." (PMID 39917660, 2024). "Proinflammatory cytokines, such as IL-1α, IL-1β, IL-6, IL-8, TNF-α and TNF-β, are associated with osteoclastogenesis, a key process leading to clinical periodontitis outcomes and periodontitis-associated inflammatory diseases." (PMID 38396821, 2024). "Focusing on the biomarkers present in the GCF, it was proved that IL-1 with both its types, IL-1α and IL-1β, possess great potential in distinguishing periodontitis from periodontal healthy cases." (PMID 36902030, 2023). "IL1A and IL1B polymorphisms were reported as noteworthy biomarkers for chronic periodontitis susceptibility in the evaluation of eight meta-analyses, by means of a Bayesian approach." (PMID 35454140, 2022). "IL-1α, IL-1β and IL-6 are proinflammatory cytokines that are thought to play a role in periodontitis development." (PMID 35571048, 2022). "A number of retrospective studies demonstrated a correlation between polymorphisms of interleukins IL-1a, IL-1b, IL-1RN, IL-6, IL-10 as well as TNF-a and the incidence of periodontitis and peri-implant disease." (PMID 35819566, 2022). "During 3 weeks of EG, IL-1β expression catches up with IL-1α and continues to increase in periodontitis." (PMID 34072136, 2021). "The most established cytokines in periodontitis patients in this regard are IL-1α, IL-β, IL-6, IL-8, and TNF-α." (PMID 34207600, 2021). "Periodontitis as an inflammatory disease has been known to increase the levels of proinflammatory cytokines, including IL-1α, IL-1β, IL-6, and TNF-α." (PMID 33383828, 2020). "Several previous meta-analyses bring results on the possible association among polymorphisms in IL1A, IL1B, IL6, IL10 and IL17A/F genes and diverse clinical aspects of periodontitis, as well as dental implant failure." (PMID 32075624, 2020). "One study indicated Prevotella induces immune response in periodontitis by regulating IL-1α and IL-1β levels." (PMID 32730353, 2020). "In a meta-analysis, it is demonstrated that IL-1α and IL-1β genetic variation are significant contributors to chronic periodontitis." (PMID 32604936, 2020). "Mean (SD) salivary IL-1α levels in periodontitis groups before and after the treatment and control group were 54.7 (31.5), 65.7 (38.31) and 97.5(66.04)." (PMID 29238418, 2017). "Before starting treatment, salivary TNF-α and IL-1α concentrations were higher in healthy control group than in periodontitis group (P< 0.05)." (PMID 29238418, 2017).
periodontitis (continued). "According to the obtained findings, salivary TNF-α and IL-1α levels were lower in patients with chronic periodontitis in comparison to control group." (PMID 29238418, 2017). "The current results showed that salivary IL-1α level was statistically different between periodontitis and control group." (PMID 29238418, 2017). "A recent meta-analysis demonstrated that IL-1A and IL-1B genetic variations are significant contributors to chronic periodontitis." (PMID 24151615, 2013). "A review and meta-analysis showed that IL-1α and IL-1β genetic variations are significant contributors to chronic periodontitis in Caucasians." (PMID 23691333, 2013). "Eleven days after the experimental periodontitis induction, the levels of IL-1α were lower in C.v. group when compared to NT group (p < 0.05)." (PMID 23171319, 2012). "Polymorphisms in IL-1 gene have been suggested to influence transcription of IL-1α and IL-1B and thereby the pathophysiology of periodontitis." (PMID 22203911, 2011). "Out of the most studied genes in aggressive periodontitis [IL1-A and IL1-B (2q14), IL-4 (5q31.1), IL-10 (1q31-q32), FcγRIIa, FcγRIIb, and FcγRIIIb (1q23), and TNFA (6p21.3)], IL-4 and TNFA map in the intervals with suggestive association results." (PMID 20383335, 2010). "In combination with IL1A -889 and IL1B +3954, the IL1RN R-allele was reported to have a relationship with periodontitis susceptibility." (PMID 20339487, 2010). "To verify whether the observed synergistic activation of the COX-2-PGE2 axis is specific for TNF, we analyzed the effect of several cytokines that are involved in periodontitis pathogenesis, including IL-1β, IL-1α, and interferon-α (IFNα)." (PMID 40178270, 2025). "Two studies reported a positive association between the IL-1α (+4,845) polymorphism and periodontitis, whereas the other studies showed a negative association." (PMID 39810806, 2024). "Correspondingly, certain variants (alleles) of genes that encode a genotype consisting of Interleukins 1A and 1B (IL1A and IL1B) were found to detect individuals (hosts) with tooth loss due to severe periodontitis after adjusting for smoking, diabetes and professional dental care." (PMID 37762554, 2023). "However, it was suggested that the distributions of IL-1B+3954 genotypes and IL-1A+4845 and IL-1B+3954 haplotypes were unique to the Japanese patients with rheumatoid arthritis and periodontitis." (PMID 36429405, 2022). "For example, a group of researchers has identified the association between the genetic risk factors of biomarkers (IL-1, IL-1β, IL-1α, IL-4, IL-10) and periodontitis in different populations, whereas others found no connection." (PMID 34684209, 2021). "The results of studies conducted in other populations indicate a lack of association between the IL-1α gene −889C/T polymorphism and aggressive periodontitis." (PMID 33327639, 2020). "Significant association between this polymorphism and elevated levels of IL-1A in localized aggressive periodontitis was identified but not risk of lung cancer in Chinese population (TT genotype - OR = 0.809, 95% CI: 0.18, 3.56, P = 0.779)." (PMID 27918732, 2017). "Comparison of mean TNF-α level between periodontitis and control groups before and after the treatment showed significant differences (P< 0.05); Although, salivary IL-1α concentration increased after the treatment, the change was not statistically significant (p=0.056)." (PMID 29238418, 2017). "Considering GCP and GAgP results together, the likelihood of periodontitis was greater in patients with IL-1A and/or IL-1 B polymorphisms than in those with neither polymorphism (OR = 8.11, 95%CI [1.85–35.48])." (PMID 29023524, 2017). "Two meta-analyses on the same SNP in IL-1A gene, rs1800587, found an association with chronic but not aggressive periodontitis." (PMID 29023524, 2017).
periodontitis (continued). "Another case-control study with Japanese adults demonstrated that the distributions of IL-1B +3954 genotypes and haplotypes of IL-1A +4845 and IL-1B +3954 were unique to patients with RA and periodontitis compared with those with periodontitis and healthy individuals." (PMID 25657893, 2015). "We can speculate that the increases in TNF-α, IL-1α, CXCL1, CCL2, and Th17 responses following testosterone GAHT therapy could increase inflammation in periodontal tissues, potentially elevating periodontitis risk." (PMID 39917660, 2024). "Moreover, the expression of proinflammatory genes, such as Il1β, Il1α, Tnf and Ccl12, decreased in the 3D-exo-treated group compared with 2D-exo-treated group, indicating that the 3D-exos exerted enhanced anti-inflammatory efficacy in the periodontitis model." (PMID 34907166, 2021). "Thus, our results suggest that allele 2 of IL-1α+4845 might be a risk indicator for CHD and severe periodontitis." (PMID 23691333, 2013). "Functional analysis revealed that both bacteria promoted the enrichment of proteins involved in the acute inflammatory response, including elevating IL-1α, IL-RN, and S100A8, which are key players in the immune response during periodontitis." (PMID 40574274, 2025). "While IL1A, IL1B, IL6, and TNFA are among the most extensively studied cytokine genes in periodontitis, numerous other pro- and anti-inflammatory mediators have been implicated in disease susceptibility, progression, and tissue destruction." (PMID 41300760, 2025). "Consistent with existing literature 45-47, periodontitis was found to elevate levels of various growth factors and inflammatory mediators, including G-CSF, IFN-γ, IFN-I, IL-1α, IL-6, and TNF-α." (PMID 40521205, 2025). "CXCL1, CXCL3, CXCL8, CSF3, IL1A, IL1B, and IL1RN all increased in JKs in periodontitis as predicted by our atlas/DEG analyses; alternatively, SKs were relatively less active compared to JKs." (PMID 38876998, 2024). "They concluded that an upsurge of pro-inflammatory interleukins i.e. interleukin-1 alpha (IL-1α), IL-1β, interleukin-12 (IL-12), and IL-6 along with TNF-α, found in periodontitis." (PMID 38196480, 2024). "IL1 superfamily members IL1A, IL1B, and IL36G were upregulated in periodontitis in both the basal and suprabasal layers of the JK; further, though previously reported, we observed concomitant expression of these genes in the peri-junctional stroma." (PMID 38876998, 2024). "Both IL-33 and IL-1α as alarmins were elevated in GCF and/or plasma in generalized aggressive periodontitis and in chronic periodontitis compared to healthy subjects." (PMID 38098978, 2023). "To confirm the inflammatory conditions within periodontitis gingiva, we observed up-regulation of SDF-1, CCL5, IL-1α, IL-4, and other inflammatory cytokine genes by qPCR." (PMID 36991451, 2023). "The aim of this study is to compare genotypes and soluble protein of pro and anti-inflammatory cytokines (IL-1α, IL-1β, IL-6, IFN-γ, IL-10, TNF-α and IL-4) in subjects with or free of chronic periodontitis." (PMID 23046796, 2012). "IL-1 receptor antagonist (IL-1RA) is an endogenous inhibitor that competes with IL-1α and IL-1β for receptor binding without activating downstream signalling; its elevation in periodontitis often reflects an inadequate compensatory response." (PMID 41583507, 2026). "IL1A, IL1B, CXCL1, and CXCL3 displayed some correlation with highly infected cells —mostly suprabasal cells, likely explaining the differentiation effects predicted for these cells in periodontitis." (PMID 38876998, 2024). "Cytokines like IL-1α, IL-1β, IL-6, IL-8, and TNF-α have been documented to be involved in immune activation, increased cytotoxic activity, and cytokine-mediated osteoclastic bone resorption in aggressive forms of periodontitis." (PMID 27642305, 2016). "In transgenic mice overexpressing IL-1α, periodontitis developed even in the absence of a significant bacterial challenge." (PMID 25077073, 2014).